HEATR3 (HEAT repeat containing 3)
Description:
Plays a role in ribosome biogenesis and in nuclear import of the 60S ribosomal protein L5/large ribosomal subunit protein uL18 (RPL5). Required for proper erythrocyte maturation.
Synonyms: hsSyo1; FLJ20718; DBA21; SYO1
Tractability: PROTAC: ubiquitination databases record sites on it; its protein half-life has been measured.
Gene: Protein-coding gene on chromosome 16 (50,065,964 to 50,107,272, forward strand). Ensembl gene ENSG00000155393.
Subcellular location (Human Protein Atlas): Nucleoplasm; Cytosol
Gene Ontology:
Biological process: erythrocyte maturation; protein import into nucleus; ribosomal large subunit biogenesis
Genetic constraint (gnomAD): Loss-of-function variants: 44 observed, 48.9 expected, observed/expected ratio (o/e) 0.9, 90% interval 0.71 to 1.16. The upper end of that interval is the gene's LOEUF score, 1.16, which puts it in group 5 of 6, group 1 being the genes least tolerant of losing a copy. Missense variants: 629 observed, 653.73 expected, observed/expected ratio (o/e) 0.96, 90% interval 0.9 to 1.03. Synonymous variants: 284 observed, 250.73 expected, observed/expected ratio (o/e) 1.13, 90% interval 1.03 to 1.25.
Homologues: Orthologues: chimpanzee HEATR3 (100% identical), macaque HEATR3 (99% identical), rabbit HEATR3 (90% identical), guinea pig HEATR3 (89% identical), pig HEATR3 (88% identical), rat Heatr3 (87% identical), mouse Heatr3 (86% identical), dog HEATR3 (82% identical), tropical clawed frog heatr3 (57% identical), zebrafish heatr3 (52% identical), Drosophila melanogaster CG10286 (26% identical).
Diseases named in the same sentence as HEATR3 in open-access papers:
HEATR3 is named in the same sentence as 17 diseases in open-access papers, as found by Europe PMC text mining. Sharing a sentence is not in itself a finding about the gene and the disease. The quoted sentences say what the papers report.
glioma (5 papers, 2019 to 2025). A benign or malignant brain and spinal cord tumor that arises from glial cells (astrocytes, oligodendrocytes, ependymal cells). "Single nucleotide polymorphisms (SNPs) at the HEATR3 locus have been reported to be associated with the development of esophageal squamous cell carcinoma, testicular germ cell tumor, and glioma." (PMID 39722126, 2024). "MR evidence robust to the FDR p-value threshold and Steiger filtering identified 3 CpG sites (cg01561092, cg05926943, cg01584448) in one genomic region (HEATR3) that have a putative association with glioma and glioblastoma risk." (PMID 37085538, 2023). "In support of these findings, MR provided evidence that higher levels of gene expression of HEATR3 in blood tissue was associated with an increased risk of glioma and glioblastoma." (PMID 37085538, 2023). "As the CpG sites reside in close genomic positions they were mapped to the same gene, a known oncogene, HEATR3, which has been associated with glioma risk in previous studies; thus, providing evidence that the genomic region is relevant." (PMID 37085538, 2023). "Here MR, colocalization and Steiger filtering offered further evidence that differential gene expression of HEATR3 within blood tissue increased the risk of glioma and glioblastoma." (PMID 37085538, 2023). "MR evidence indicated that DNAm at 3 CpG sites (cg01561092, cg05926943, cg01584448) in one genomic region (HEATR3) had a putative association with glioma and glioblastoma risk (False discovery rate [FDR] < 0.05)." (PMID 37085538, 2023). "Similarly, ABC links rs11643164 (16q12.1) to HEATR3, a key regulator of ribosome biogenesis, as a candidate target gene for ccRCC susceptibility, with a prior evidence for an association with glioma risk." (PMID 41326661, 2025). "The influence of certain genes, such as DNA2, EGFR, FAIM, and HEATR3, on glioma risk, which is mediated through alterations in telomere length, enhances the elucidation of pathogenic mechanisms and introduces novel strategies for targeting telomere‐related pathways." (PMID 39722126, 2024). "For three genes (HEATR3, PHLDB1 and RTEL1) there were both expression and splicing causal effects on glioma risk, and for one gene (EGFR) there were both expression and protein abundance causal effects on glioma risk)." (PMID 39565278, 2025). "Additionally, it was observed that the mediation effects of DNA2 and HEATR3 via telomere length were in the opposite direction to their respective total effects, suggesting a potential masking effect, wherein these genes may diminish part of the glioma risk effect size by reducing telomere length." (PMID 39722126, 2024). "Variants in 1q32.1 (MDM4), 16q12.1 (HEATR3), 22q13.1 (SLC16A8) and 11q14.1 were also associated with increased risk of IDH-wt glioma although the results were not significant after adjusting for multiple comparison." (PMID 31842352, 2019).
glioblastoma (3 papers, 2019 to 2023). The most malignant astrocytic tumor (WHO grade IV). "In recent findings, genetic variants related to HEATR3 have been associated with increased risk of glioblastoma and esophageal cancer." (PMID 31249589, 2019).
esophageal cancer (2 papers, 2019 to 2025). A primary or metastatic malignant neoplasm involving the esophagus. "Other studies have identified this as a risk gene associated with esophageal cancer and have observed an increased expression of HEATR3 in bladder cancer." (PMID 40050615, 2025).
fibroids (2 papers, 2019 to 2025). "We also find that increased predicted expression of HEATR3 in uterine tissue is associated with fibroids across ancestry strata." (PMID 40050615, 2025). "Increasing GPGE of HEATR3 in skeletal muscle was positively associated with fibroids and SMR analyses suggested increasing HEATR3 expression in the uterine tissue is positively associated with uterine fibroids." (PMID 31249589, 2019). "Among novel loci, sentinel SNP rs4785384, on chromosome 16q12.1 near HEAT repeat containing 3 (HEATR3) was most significantly associated with fibroids (T allele Odds Ratio [OR] = 1.08; 95% confidence interval [CI]: 1.05, 1.10; P = 1.45 × 10-9; heterogeneity p [P-Het] = 0.38)." (PMID 31249589, 2019). "We identified one significant and colocalized gene in uterine tissue, HEATR3 (HEAT repeat protein 3), with an increased gene expression associated with risk of fibroids." (PMID 40050615, 2025).
bladder cancer (1 paper, 2024). "A recent study also found that HEATR3 is involved in cell proliferation, metastasis, and cell cycle development in bladder cancer, exerting a pro‐tumourigenic role." (PMID 39722126, 2024).
chordoma (1 paper, 2023). Chordomas are rare malignant tumors arising from embryonic remnants of the notochord in axial skeleton. "Several candidate genes, including OTUD5, CDK6, LUC7L2, IER3IP1, and HEATR3, were not linked to other chordoma dependency genes following either of these two approaches." (PMID 37024492, 2023).
melanoma (1 paper, 2021). A malignant, usually aggressive tumor composed of atypical, neoplastic melanocytes. "Akt was associated with the telomerase-reverse transcriptase catalytic subunit HEATR3, which may be activated by Akt in melanoma." (PMID 33557837, 2021).
mycobacterial infections (1 paper, 2022). "Of 15 prioritized in this study genes, four genes, namely GBP2, HEATR3, PPP1R9B and KDM6A, exhibited an elevated transcriptional level in whole blood, spleen or EBV-transformed lymphocytes, thus lending additional support to their role in increasing susceptibility to mycobacterial infections." (PMID 36338958, 2022).
uterine fibroids (1 paper, 2019). "HEATR3, located in 16q12.1 was the most significant association in SMR analyses, and its gene expression was positively associated with uterine fibroids (βSMR= 0.165; P-value 1.1 × 10-5)." (PMID 31249589, 2019).
HEATR3 also shares sentences with these, for which no sentence is quoted: tumour (3 papers); blood cancer (1); cancer (1); chronic lymphocytic leukemia (1); colorectal cancer (1); esophageal squamous cell carcinoma (1); Ewing sarcoma (1); testicular germ cell tumor (1).